TUBB1 (tubulin beta 1 class VI)
Diseases named in the same sentence as TUBB1 in open-access papers:
TUBB1 is named in the same sentence as 54 diseases in open-access papers, as found by Europe PMC text mining. Sharing a sentence is not in itself a finding about the gene and the disease. The quoted sentences say what the papers report.
Thrombocytopenia (12 papers, 2013 to 2025). A reduction in the number of circulating thrombocytes. "Deficiency in TUBB1 leads to thrombocytopenia, whereas overexpression is associated with formation of large platelets and platelet hyperaggregation." (PMID 36414707, 2022). "Thrombocytopaenia was a feature in patients with TUBB1 mutations studied by other groups." (PMID 30446499, 2018). "Moreover, mutations in cytoskeleton-associated proteins, such as FLNA, ACTN1, MYH9, or TUBB1, were identified in patients affected by proplatelet defects and thrombocytopenia." (PMID 30336771, 2018). "This discrepancy could be explained by another factor, different from the TUBB1 mutation, which could induce thrombocytopaenia." (PMID 30446499, 2018). "By labeling a few proteins, a potential abnormality could be identified or narrowed-down to a group of IPDs featured by cytoskeleton alterations (e.g., FLNA-related thrombocytopenia, FLNA-RT, TUBB1-related thrombocytopenia, TUBB1-RT, and WAS)." (PMID 32079152, 2020). "This technique facilitates the phenotypic diagnosis of a BSS, α-granule deficiency-related macrothrombocytopenias (e.g., GPS and GFBI1-related thrombocytopenia), and TUBB1- and FLNA-related thrombocytopenia." (PMID 33800006, 2021).
Macrothrombocytopenia (10 papers, 2011 to 2026). "Reviewing TUBB1 and its genetic variations in macrothrombocytopenia to date, we found that reported mutations in mammals included 2 missense mutations, p.R318W and p.F260S in exon 4 in humans, and a missense mutation of p.D249N in canines." (PMID 32892537, 2021). "TUBB1 encodes for β1-tubulin and mutations within TUBB1 are associated with an autosomal dominant form of IT known as a congenital macrothrombocytopenia." (PMID 31275945, 2019). "Mutations in these genes have been associated with macrothrombocytopenia (TUBB1,), mitochondrial complex V (ATP synthase) deficiency nuclear type (ATP5E,) or even tumour metastasis (CTSZ,)." (PMID 25710380, 2015). "Interestingly, GFI1B loss also causes a macrothrombocytopenia phenotype in mice, and in our data, TUBB1 expression decreases quickly as a function of decreased GFI1B expression but then plateaus at a level that corresponds to loss of one copy of TUBB1." (PMID 41532405, 2026). "This raises the hypothesis that low GFI1B levels may cause macrothrombocytopenia at least partially via reducing TUBB1 expression." (PMID 38464330, 2025). "Finally, given that the synonymous TUBB1 p.T178T variant was found in all of our healthy control and patient samples, it is unlikely that this variant is associated with macrothrombocytopenia." (PMID 32892537, 2021). "Further clinical and functional studies of the newly identified TUBB1 variants may offer important insights into their pathogenicity in macrothrombocytopenia." (PMID 32892537, 2021). "In summary, our findings suggest that further functional and clinical analyses of the new TUBB1 variants that we identified in macrothrombocytopenia patients may provide new insights into the molecular mechanisms of normal and abnormal platelet production and morphology." (PMID 32892537, 2021). "Congenital macrothrombocytopenia is observed in individuals with MYH9 disorders, heterozygous and homozygous Bernard‐Soulier syndrome, type 2B von Willebrand disease, TUBB1 mutations, ACTIN1 mutations, etc.." (PMID 41503871, 2026). "In keeping with this observation, disruption of the MK-specific TUBB1 (β1-tubulin) in mice, dogs and human patients leads to macrothrombocytopenia 18,19." (PMID 23311859, 2013). "Mutations in TUBB1 disrupt PPF, causing macrothrombocytopenia through impaired platelet maturation." (PMID 41503871, 2026). "Of these, ACTN1, which encodes alpha-actinin 1, was regarded as the most likely candidate by virtue of its functional role in the cytoskeleton and by analogy to some of the known macrothrombocytopenia genes, such as MYH9, FLNA and TUBB1." (PMID 24069336, 2013).
breast carcinoma (3 papers, 2016 to 2021). "TubB1 expression is correlated with taxane resistance in breast cancer." (PMID 35008169, 2021). "TubB1 is the most common isotype in human lung cancer and breast cancer cell lines." (PMID 35008169, 2021).
congenital hypothyroidism (2 papers, 2018 to 2023). A thyroid hormone deficiency present from birth. "Using whole exome sequencing, we uncovered an homozygous missense mutation in TUBB1 gene, in two siblings of a consanguineous family with congenital hypothyroidism and thyroid dysgenesis (TD)." (PMID 30446499, 2018).
melanoma (2 papers, 2021 to 2023). A malignant, usually aggressive tumor composed of atypical, neoplastic melanocytes. "Based on correlation analysis between PDC6IP and 83 MTEX proteins differentiating melanoma patients with PD from those with NED/SD, we found four proteins that strongly (ru > 0.7, P < 0.005) associated with PDC6IP, namely HSP90AB1, PFN1, TUBB, and TUBB1." (PMID 33613873, 2021). "TUBB, TUBB1, TUBB2A, TUBB4A and TUBB4B belong to the tubulin family, and gene expression analyses showed a higher expression of all these tubulins in melanoma compared to normal skin." (PMID 37291228, 2023). "Hence, the molecular signature of MTEX consisting of PDCD6IP/ALIX, 4 correlated proteins (HSP90AB1, TUBB, TUBB1, and PFN1) highly expressed in MTEX of patients with PD, plus CNTN1 and TGF‐β1 with differential distribution in MTEX of PD vs NED/SD patients may have prognostic significance in melanoma." (PMID 33613873, 2021).
neuroblastoma (2 papers, 2022 to 2025). Neuroblastoma (NB) is the most common solid, extracranial childhood tumor. "Seven of our hits (Tubb1, Tubb5, Eef1a1, Eef1g, Gapdh, Nudc, Actg1) are present in their list of 52 enriched proteins from TGM2 stimulated N2a neuroblastoma cells." (PMID 41142754, 2025).
thyroid dysgenesis (2 papers, 2018 to 2025). "The authors identified three novel mutations in the TUBB1 gene, in homozygous or heterozygous state, in patients with thyroid dysgenesis and large platelets." (PMID 41303336, 2025). "The common feature in TUBB1 mutation carriers is thyroid dysgenesis and abnormal platelet morphology." (PMID 30446499, 2018).
athyreosis (1 paper, 2018). Athyreosis is a form of thyroid dysgenesis characterized by complete absence of thyroid tissue that results in primary congenital hypothyroidism, a permanent thyroid deficiency that is present from birth. "None of the patients in our cohort with TUBB1 mutations had athyreosis." (PMID 30446499, 2018).
chronic hepatitis (1 paper, 2025). An active inflammatory process affecting the liver for more than six months. "Among the participants with positive HBeAg, those who had raised ALT during the HBeAg-positive chronic hepatitis phase exhibited lower TUBB1 promoter methylation levels than those with normal ALT, who were in the HBeAg-positive chronic infection phase." (PMID 41065418, 2025). "Among HBeAg-positive patients, those who experienced an elevation in ALT levels during the HBeAg-positive chronic hepatitis phase exhibited lower levels of TUBB1 promoter methylation compared to patients with normal ALT values who were in the HBeAg-positive chronic infection phase." (PMID 41065418, 2025). "The TUBB1 promoter methylation levels showed a sequential decrease in the order of HBeAg-positive chronic infection, HBeAg-positive chronic hepatitis, HBeAg-negative chronic infection, and HBeAg-negative chronic hepatitis." (PMID 41065418, 2025).
Congenital thrombocytopenia (1 paper, 2024). Thrombocytopenia with congenital onset. "TUBB1 expression is critical for platelet biogenesis, representing 50 to 90% of cytoplasmic β-tubulin, and defects in its function lead to congenital thrombocytopenia." (PMID 39725029, 2024).
COVID-19 (1 paper, 2023). A disease caused by infection with severe acute respiratory syndrome coronavirus 2. "The remaining 8 key genes (EGR2, HIST1H3H, HIST1H4H, HIST1H4I, HIST1H4K, MTHFD2, TUBA4A, and TUBB1) were less studied in the roles of COVID-19 and OA, emphasizing their importance in future research." (PMID 37291167, 2023).
glioma (1 paper, 2025). A benign or malignant brain and spinal cord tumor that arises from glial cells (astrocytes, oligodendrocytes, ependymal cells). "In a follow up study by the same group using C6 glioma cells, 4 of our hits (Tubb1, Tubb5, Actg1 and Kif5b) were present out of a list of 22 enriched proteins." (PMID 41142754, 2025).
hypothyroidism (1 paper, 2018). Abnormally low levels of thyroid hormone. "A TUBB1 mutation screening study in patients with hypothyroidism and altered MPV and/or a history of thrombotic disease would be of great interest." (PMID 30446499, 2018). "A TUBB1 mutation screening study in patients with non‐autoimmune, non‐postsurgical hypothyroidism and altered mean platelet volume and/or a history of thrombotic disease should be considered." (PMID 30446499, 2018). "The Tubb1−/− mice have large platelets and show hypothyroidism, in accordance with the phenotype in mutated patients." (PMID 30446499, 2018). "Our experiments in Tubb1−/− mice provided the first evidence of a role for β1‐tubulin in TD and hypothyroidism." (PMID 30446499, 2018). "At 3 months of age, serum TSH levels were higher and T4 levels lower in Tubb1−/− than in wild‐type mice, suggesting hypothyroidism in the mutants." (PMID 30446499, 2018). "In sum, our findings in Tubb1−/− mice demonstrate a complex mechanism of hypothyroidism involving early abnormal proliferation of progenitors, delayed thyroid migration, defective thyroid differentiation, impaired thyroid hormone release and structural disorganization of the thyroid tissue." (PMID 30446499, 2018).
liver fibrosis (1 paper, 2025). "Despite these findings, research on the function of TUBB1 remains limited, particularly regarding its potential mitigating role in reversing liver fibrosis." (PMID 40006040, 2025). "We provide a new perspective for TUBB1 as a potential therapeutic target of quercetin in liver fibrosis." (PMID 40006040, 2025). "The univariate logistic regression analysis indicates that the three hub genes affect the occurrence of liver fibrosis, as follows: CDKN1A with an odds ratio (OR) of 1.22 (95% CI: 1.08–1.39), NR1I3 with an OR of 0.92 (95% CI: 0.87–0.89), and TUBB1 with an OR of 0.95 (95% CI: 0.80–1.16)." (PMID 40006040, 2025).
malaria (1 paper, 2022). Malaria is a serious and sometimes fatal disease caused by a parasite that commonly infects a certain type of mosquito which feeds on humans. "In the liver, Myh10, Tubb1, and Notch4 were constitutively expressed and their expression responded to both blood-stage malaria and vaccination." (PMID 35214745, 2022).
non-small cell lung carcinoma (1 paper, 2021). A group of at least three distinct histological types of lung cancer, including non-small cell squamous cell carcinoma, adenocarcinoma, and large cell carcinoma. "Cabazitaxel targets the MPM genes, TUBB1 and TUBA4A, and was effective in treating non-small cell lung cancer (NSCLC) that was resistant to docetaxel, a drug that targets TUBB1 along with other known interactors of MPM genes." (PMID 33916178, 2021).
post-traumatic stress disorder (1 paper, 2020). An anxiety disorder precipitated by an experience of intense fear or horror while exposed to a traumatic (especially life-threatening) event. "Another module downregulated in the early adversity group was related to platelet activation and wound healing (hub genes: GP9, CMTM5, TUBB1, GNG11, PF4), and resembled a co-expression module previously found over-expressed in post-traumatic stress disorder resilient soldiers." (PMID 32066736, 2020).
somatotropinomas (1 paper, 2018). "By contrast, TUBB1 (tubulin beta 1 class VI) was upregulated in AIPmut positive somatotropinomas (5.16-fold change, P = 0.0078 vs. normal pituitary)." (PMID 29507682, 2018).
thyroid (1 paper, 2018). "To further investigate the implication of TUBB1 gene mutations in thyroid disease, we transfected the mutations into the Nthy‐ori 3‐1 cell line." (PMID 30446499, 2018). "This is the first time that TUBB1 mutations are associated with thyroid dysgenesis, in addition to abnormal platelet physiology." (PMID 30446499, 2018). "Our results highlight a hitherto unsuspected role for a specific tubulin isotype, Tubb1, in thyroid development and disease and extend our knowledge on genetic background of CH." (PMID 30446499, 2018). "Thus, our work provides novel insights into the role of the Tubb1 isotype in thyroid physiopathology and in platelet function and therefore expands the spectrum of the rare paediatric diseases related to tubulin mutations and microtubule dysfunction." (PMID 30446499, 2018).
thyroid disorders (1 paper, 2018). "In contrast, in previous studies, humans with TUBB1 mutations and Tubb1−/− mice had macrothrombocytopaenia but no reported thyroid disorders." (PMID 30446499, 2018).
thyroid hypoplasia (1 paper, 2018). Thyroid hypoplasia is a form of thyroid dysgenesis characterized by incomplete development of the thyroid gland that results in primary congenital hypothyroidism, a permanent thyroid deficiency that is present from birth.
cancer (7 papers, 2017 to 2024). A tumor composed of atypical neoplastic, often pleomorphic cells that invade other tissues. "Since paclitaxel is known to target BCL2 and TUBB1, we used pan-cancer genomic data from hundreds of patients to show that a single-nucleotide variant in the BCL2 sequence can predict a patient’s response to paclitaxel." (PMID 31044156, 2019). "Several housekeeping genes, such as ACTB, TUBB1, and PTMA, as well as noncoding RNAs, such as srpRNA (RN7SL2), are highly abundant in the plasma of both cancer patients and HDs." (PMID 35816095, 2022). "Other drug targets for cancer therapeutics with high CAP scores include MAP4 (60%) and TUBB1 (30%), which are targets of paclitaxel, MAP1A (42%), a target of estramustine, CD3G (39%), a target of muromonab, and PARP1 (37%), a target of olaparib." (PMID 29273096, 2017).
tumor (3 papers, 2015 to 2024). "We found that taxane-resistant tumor showed elevated expression levels of TUBB1 and lower expression levels of TUBB3, TUBB4B, and TUBB6 genes when compared with the sensitive tumors." (PMID 30126203, 2018). "TUBB1 Albahde (2020) found that TUBB1, a member of the tubulin superfamily, is overexpressed in PDAC, with its downregulation leading to reduced cellular proliferation, invasiveness, and tumor growth." (PMID 39575418, 2024).
Respiratory disease (2 papers, 2013 to 2020). "Respiratory disease biomarkers like ARG2, SCNN1G, EPB41L4B, CSF1, PTEN, TUBB1, and ESR2 were also detected." (PMID 24382964, 2013).
TUBB1 also shares sentences with these, for which no sentence is quoted: infection (3 papers); platelet disorders (3); Alzheimer disease (1); atherosclerosis (1); bacterial infection (1); bleeding disorder (1); cardiac diseases (1); cardiovascular disease (1); chronic hepatitis B (1); Chronic myeloid leukemia (1); congenital anemia (1); factor V deficiency (1); hereditary thrombocytopenia (1); HIV-1 infection (1); homocystinuria (1); Hypercholesterolemia (1); Hypertension (1); hypertriglyceridemia (1); Impaired glucose tolerance (1); Jacobsen syndrome (1); liver disease (1); myocardial infarction (1); neurological disorders (1); osteoporosis (1); ovarian carcinoma (1); Primary hypothyroidism (1); prostate carcinoma (1); renal carcinoma (1); sarcopenia (1); thrombotic disease (1).